DYRK1A (dual specificity tyrosine phosphorylation regulated kinase 1A)
Diseases named in the same sentence as DYRK1A in open-access papers (continued):
Sharing a sentence is not in itself a finding about the gene and the disease.
glioblastoma (29 papers, 2014 to 2025). The most malignant astrocytic tumor (WHO grade IV). "In glioblastoma, DYRK1A causes cell cycle arrest via phosphorylating the DREAM complex component LIN52." (PMID 33924599, 2021). "We report that partial DYRK1A inhibition increases proliferation and reactivates cell cycle of dormant RB-deficient glioblastoma cells, thereby improving efficacy of anti-proliferative drugs." (PMID 33863878, 2021). "Abnormal DYRK1A expression is also linked to a raft of malignancies like glioblastoma multiforme, gastrointestinal stromal tumors, lung cancer, melanoma, and leukemias (AML, AMLK, and ALL)." (PMID 34832952, 2021). "In contrast, evidence suggests that elevated expression of DYRK1A leads to destabilization of hypoxia-inducible factor 2α, loss of glioblastoma stemness and inhibition of tumour growth." (PMID 33863878, 2021). "In addition to neurological disorders, DYRK1A dysregulation has been linked to cancer (especially lung and pancreatic cancers), glioblastoma, melanoma, leukemia, diabetes, and heart diseases." (PMID 36012629, 2022). "In glioblastoma cells, DYRK1A phosphorylates ubiquitin ligase CDC23, which mediates mitotic protein degradation, thereby promoting tumor growth." (PMID 39436397, 2024). "Despite having important cell cycle regulatory functions, a role for DYRK1A in cancer, other than glioblastoma remains to be fully investigated." (PMID 38839871, 2024). "Further studies characterized the DYRK1A interactomes using either ectopic expression in the human glioblastoma cell line T98G, or endogenous DYRK1A immunoprecipitated from HeLa cells." (PMID 37900285, 2023). "Dual specificity tyrosine phosphorylation regulated kinase 1A (DYRK1A) demonstrates its tumor suppressive function by mediating phosphorylation of Tyr15 and Thr161 in glioblastoma cells." (PMID 37311884, 2023). "For example, Recasens and colleagues recently revealed by phosphoproteomics in the context of glioblastoma that DYRK1A functions as a tumor suppressor." (PMID 36012629, 2022). "Inhibiting DYRK1A/B in the glioblastoma model with VER‐239353 forced the cells to exit G0 and enter G1 but not actively undergo cell cycling." (PMID 34708541, 2021). "DYRK1A inhibition promoted EGFR degradation in glioblastoma cells, which sharply reduced the self-renewal and proliferation of cancer cells." (PMID 33500384, 2021). "Collectively, while these observations make it clear that DYRK1A is an important kinase in glioblastoma, they also suggest that the function of DYRK1A in glioblastoma, and probably in other tumours, is dependent on the cell type and its genetic background." (PMID 33863878, 2021). "Here, we also observed increased cyclin B1, A and D1 expression in U87MG glioblastoma cells following complete DYRK1A/B inhibition with VER‐239353." (PMID 34708541, 2021). "As DYRK1A is a potential therapeutic target to glioblastoma growth, more work needs to be achieved to profoundly elucidate underlying mechanism." (PMID 34109727, 2021). "To quantify changes to signalling of glioblastoma cells induced by DYRK1A inhibition, we employed the EasyPhos phosphoproteomics workflow." (PMID 33863878, 2021). "Inhibition of DYRK1A promotes EGFR degradation in primary glioblastoma cell lines and neural progenitor cells, sharply reducing the self‐renewal capacity of normal and tumorigenic cells." (PMID 34109727, 2021). "Inhibition of DYRK1A in glioblastoma stem cell induces degradation of epidermal growth factor receptor (EGFR), resulting in decreased self-renewal of EGFR-addicted cells." (PMID 33863878, 2021). "Taken together, these results suggest that DYRK1A limits the self-renewal ability of glioblastoma stem cells, and DYRK1A expression/activity is necessary for differentiation commitment." (PMID 33924599, 2021).
glioblastoma (continued). "Mechanistically, we delineate a novel DYRK1A-CDK5-SOX2 pathway underlying self-renewal potential of glioblastoma stem cells and show that DYRK1A activity is necessary for the differentiation of glioblastoma stem cells." (PMID 33924599, 2021). "We show that DYRK1A inhibition results in a block to glioblastoma stem cells differentiation and that DYRK1A inhibition insulates the self-renewing population of GSCs from potent differentiation-inducing signals." (PMID 33924599, 2021). "DYRK1A inhibition or polypeptide derived from DYRK1A‐targeted motif of NFATc1, clearly destabilized NFATc1 protein and impaired glioblastoma migration." (PMID 34309232, 2021). "To validate the DYRK1A-CDK5-SOX2 axis in glioblastoma cells, we analysed how DYRK1A inhibition changes SOX2 expression in CDK5-depleted cells." (PMID 33924599, 2021). "We found that DYRK1A was highly expressed in glioma and glioblastoma cells, and its expression was positively correlated with that of NFATC1." (PMID 34309232, 2021). "Additionally, other Dyrk1A inhibitors such as pyrrolopyrimidine derivatives suppressed the growth of glioblastoma xenografts." (PMID 38893153, 2024). "Furthermore, DYRK1A expression positively correlates with EGFR levels, and DYRK1A inhibitors reduce EGFR-dependent glioblastoma growth." (PMID 39436397, 2024). "DYRK1A could be especially relevant to the progression of glioblastoma since it has been also shown to control the ID2-HIF2α pathway, whereby the DYRK1A inhibition could block the HIF2α degradation and promote the tumor growth (Lee SB." (PMID 37900285, 2023). "For instance, DYRK1A could activate NFATC1 to increase the migration ability of glioblastoma cells, while it could play an important role in maintaining cancer stemness in oral squamous cell carcinoma." (PMID 35655269, 2022). "In addition, DYRK1A enhanced the migration ability of glioblastoma cells by activating NFATC1 in vitro." (PMID 35655269, 2022). "Importantly, however, our discovery that DYRK1A attenuates CDK5 activity is important for the translation of DYRK1A inhibitors into glioblastoma therapy." (PMID 33924599, 2021). "To examine whether TRAF2-promoted proliferation of glioblastoma cells is mediated through DYRK1A, we first performed shRNA-mediated knockdown of DYRK1A using lentiviruses." (PMID 34117217, 2021). "Additionally, this study supports the notion that DYRK1A is a tumour suppressor kinase, at least in glioblastoma." (PMID 33924599, 2021). "Most importantly, our data suggest that DYRK1A inhibition reduces glioblastoma migration." (PMID 34309232, 2021). "In this study, we examine the role of DYRK1A in glioblastoma stem cell regulation." (PMID 33924599, 2021). "Furthermore, DYRK1A mRNA expression negatively correlated (p < 0.005) with CDK5 mRNA expression in the TCGA glioblastoma dataset, which is in line with mechanistic data presented here." (PMID 33924599, 2021). "Lastly, we addressed RB and DYRK1A cooperativity in dormant glioblastoma cells." (PMID 33863878, 2021). "DYRK1A inhibitors might have a limited value in efforts to target glioblastoma, as DYRK1A inhibition would most likely support the self-renewal programs in GSC." (PMID 33924599, 2021). "Importantly, we established that the phenotypic response of glioblastoma cells to DYRK1A inhibition depends on both retinoblastoma (RB) expression and the degree of residual DYRK1A activity." (PMID 33863878, 2021). "In this study, we delineate a novel DYRK1A signalling pathway in glioblastoma stem cells." (PMID 33863878, 2021). "In order to delineate how DYRK1A downregulates SOX2 expression, we analysed our proteomic and phosphoproteomic data obtained from U251 glioblastoma cells infected with doxycycline (DOX)-inducible DYRK1A shRNA (sh-DYRK1A U251) or treated with DYRK1A inhibitor ALGERNON." (PMID 33924599, 2021). "Aberrant expression of DYRK1A is detected in glioblastomas tissue." (PMID 34109727, 2021).
glioblastoma (continued). "Herein, we performed a detailed investigation to delineate the role of DYRK1A in glioblastoma." (PMID 33863878, 2021). "Recently, harmine was found to synergize with the anthracycline doxorubicin in the breast cancer cell line MCF-7 and harmine-mediated inhibition of DYRK1A destabilized epidermal growth factor receptor (EGFR) in aggressive glioblastomas and reduced EGFR-dependent glioblastoma growth." (PMID 29977157, 2018). "Importantly, a recent study validated Dyrk1A as a new target in EGFR–dependent glioblastoma: inhibition of Dyrk1A promoted degradation of EGFR and sharply decreased tumor cell growth and viability." (PMID 24676346, 2014). "Additionally, DYRK1A/B inhibition may sensitize glioblastoma cells to drugs that exert their effects in the G1 phase of the cell cycle, for example CDK4 or MEK inhibitors." (PMID 34708541, 2021). "The kinase activity of DYRK1A may also be induced by MEF2D in glioblastoma cell lines." (PMID 34109727, 2021). "DYRK1A interactome has been studied in different cell types, including HeLa, HEK293T, human glioblastoma T98G, and human neuroblastoma SH-SY-5Y cell lines, which led to a list of 552 interactors (BioGRID)." (PMID 40182141, 2025). "In glioblastoma stem cells, DYRK1A mimics the effect of BMP4, a member of the TGF family of cytokines, reduces cellular SOX2 levels, and promotes the differentiation of glioblastoma stem cells." (PMID 39482615, 2024). "Recently, it was reported that DYRK1A inhibition decreases metastases in tumors other than CRC, e.g., triple-negative breast cancer and glioblastoma cells." (PMID 35454940, 2022). "Polypeptides derived from the DYRK1A‐targeted motif of NFATC1, by competitively blocking DYRK1A kinase activity on NFATC1, clearly destabilized NFATC1 protein and impaired glioblastoma migration." (PMID 34309232, 2021). "Complete DYRK1A inhibition, as would be expected here with VER‐239353, resulted in cyclin B1 stabilization and accumulation in glioblastoma cells leading to CDK1 inhibition and cell cycle arrest." (PMID 34708541, 2021). "Inhibition of DYRK1A in glioma cells destabilizes EGFR and reduces EGFR-dependent glioblastoma growth." (PMID 34117217, 2021). "In summary, this study demonstrates that DYRK1A plays a substantial role in promoting GSC differentiation, in addition to its role in the cessation of the cell cycle in glioblastoma cells." (PMID 33924599, 2021). "Together, these findings confirm that DYRK1A negatively regulates SOX2 expression via CDK5 pathway and thus is necessary for the differentiation commitment of glioblastoma stem cells." (PMID 33924599, 2021). "In this study, we demonstrate that glioma tissues and glioblastoma cells with high expression levels of DYRK1A exhibit strong NFATC1 activity, revealing a remarkably positive correlation between DYRK1A and NFATC1." (PMID 34309232, 2021). "Thus, DYRK1A prevents epidermal growth factor receptor (EGFR) endocytosis-mediated degradation in neural stem cells and indeed, DYRK1A-dependent EGFR stabilization has been described in glioblastoma (GBM) and non–small cell lung cancer (NSCLC) cell lines." (PMID 32751160, 2020). "In the study presented here, we did not observe increased cell cycling of quiescent glioblastoma cells upon DYRK1A/B inhibition with VER‐239353." (PMID 34708541, 2021). "In conclusion, DYRK1A activated NFATC1 and increased glioblastoma migration." (PMID 34309232, 2021). "Furthermore, DYRK1A suppression can promote the degradation of EGFR and reduce the self-renewal capacity of glioblastoma cells." (PMID 34445786, 2021). "In summary, DYRK1A knockdown increased the expression of cyclin B in glioblastoma stem cells, regardless of their molecular background." (PMID 33863878, 2021). "Furthermore, it was reported that inhibition of DYRK1A destabilizes EGFR and reduces EGFR-dependent glioblastoma growth." (PMID 34445786, 2021).
glioblastoma (continued). "In glioblastoma (GBM), DYRK1A was found to be highly expressed in EGFR-amplified tumors, whereas doxycyclin-inducible shRNA depletion of DYRK1A decreased tumor growth in the orthotopic xenograft models." (PMID 37900285, 2023). "In gliomas, it has been reported that DYRK1A may destabilize HIF2-alpha in hypoxic conditions by phosphorylating thr27 of ID2, leading to reduced self-renewal of glioma stem cells, the inhibition of tumor growth, and more favorable outcomes for patients with glioblastoma." (PMID 31035417, 2019).
autism (24 papers, 2015 to 2026). Persistent deficits in social interaction and communication and interaction as well as a markedly restricted repertoire of activity and interest as well as repetitive patterns of behavior. "Haploinsufficiency of Dyrk1a, which encodes the dual-specificity tyrosine phosphorylation regulated kinase 1A (DYRK1A), has been causally linked to autism." (PMID 41559452, 2026). "The novel tank diving assay also revealed anxiolytic activity in znf536 KO zebrafish, similar to a knockout of the dyrk1aa ortholog of the DYRK1A autism risk gene." (PMID 38331943, 2024). "Remarkably, two of the PTCHD1-specific interactors are independently associated with autism (DYRK1A and DDX3X) and 11 have been previously identified as PTCHD1 interactors in mouse brain lysates." (PMID 36769003, 2023). "Strong candidate genes such as CHD8, POGZ and DYRK1A were previously reported to be associated with not only autism but also gastrointestinal issues, facial dysmorpisms, visual and feeding problems." (PMID 33338084, 2020). "DYRK1A [dual specificity tyrosine-(Y)-phosphorylation-regulated kinase 1 A] is a high-confidence autism risk gene that encodes a conserved kinase." (PMID 32467234, 2020). "We noticed genes associated with autism (members of the FoxP family and DYRK1A) to be HuR-bound and wanted to determine if targets of HuR were enriched for genes related to autism." (PMID 27383233, 2016). "In humans, truncating mutations in the DYRK1A gene cause primary microcephaly and autism." (PMID 26137553, 2015). "To validate DYRK1A as an autism candidate gene, we generated and characterized a dyrk1aa KO zebrafish model using behavioral tests and molecular techniques." (PMID 29021890, 2017). "Although some functional roles of DYRK1A have been implied in mouse studies, so far there have been no reported behavioral studies of adult knockout animals with respect to autism." (PMID 29021890, 2017). "Neurobehavioral analysis revealed that heterozygous mutants in adulthood are deficient in motor function and learning; however, none of these murine model studies present sufficient evidence to directly link Dyrk1a dysfunction with autism in the context of social interaction of an ASD animal model." (PMID 29021890, 2017). "However, given embryonic lethality in homozygous knockout (KO) mice, no murine model studies could present sufficient evidence to link Dyrk1a dysfunction with autism." (PMID 29021890, 2017). "Although vascular defects had not been directly associated with human DYRK1A haploinsufficiency syndrome, it has been reported that nearly 75% of children with autism, some of which may have DYRK1A mutations or its reduced activity, exhibited hypoperfusion in the brain detected by neuroimaging." (PMID 31043432, 2019).
autism spectrum disorder (16 papers, 2021 to 2026). A spectrum of developmental disorders that includes autism, and Asperger syndrome. "DYRK1A variants lead to a distinct congenital syndrome that commonly includes autism spectrum disorder, and Dyrk1a was shown to regulate cell-cycle progression during neurogenesis in X. tropicalis." (PMID 34739029, 2021). "In addition, DYRK1A malfunction is associated with various other neurodevelopmental disorders such as autism spectrum disorder." (PMID 37802655, 2023). "This may explain the association of altered Dyrk1A activity with cerebellum-associated diseases such as autism spectrum disorder and locomotive difficulties, motor learning impairment, and reduced exploratory behavior in children diagnosed with DS." (PMID 34090874, 2021). "This link opens up the exciting possibility to investigate and decipher the contribution of mitochondrial dysfunction in the many clinical aspects of dysfunctional DYRK1A including DYRK1A-related syndrome, Autism Spectrum Disorder, and Down syndrome." (PMID 34257281, 2021). "Mutations in dual-specificity tyrosine phosphorylation-regulated kinase 1A (DYRK1A) represent one of the most prevalent monogenic causes of neurodevelopmental disorders (NDDs), often associated with intellectual developmental disorder and autism spectrum disorder." (PMID 40182141, 2025).